TNF (tumor necrosis factor)
Diseases named in the same sentence as TNF in open-access papers (continued):
Sharing a sentence is not in itself a finding about the gene and the disease.
anemia (continued). "PCa metastasis is directly linked to elevated IL-6 and TNF-α levels, which in turn drive an upsurge in CRP and FIB levels in the body, prevent iron from being absorbed as the building block of hemoglobin, and worsen anemia." (PMID 41142623, 2025). "In addition, inflammatory cytokines including tumor necrosis factor and interleukin-1 directly inhibit the activity of red blood cell production, further leading to anemia." (PMID 41204476, 2025). "Our group also had positive anti-TNF-α effects in regulating anemia severity as well." (PMID 38612376, 2024). "Anti-TNF-α therapy could improve anemia in IBD patients by downregulating hepcidin expression and normalizing iron metabolism." (PMID 38612376, 2024). "Thus, TNFα, IL-1β, IL-6 and IFN-γ seem to be responsible for impaired EPO synthesis in the development of anemia associated with inflammation." (PMID 37240288, 2023). "Another limitation is due to the lack of testing materials, we were unable to assess iron parameters like serum iron level and ferritin level (we have not investigated iron deficiency anemia) and inflammatory cytokines like IL-6 and TNFα." (PMID 37344827, 2023). "In severe anemia, low IL-10 levels might allow patients to produce enough TNF to interfere with erythropoiesis and erythrophagocytosis." (PMID 36668942, 2023). "In addition, TNFα can induce anemia in patients with MM by directly inhibiting the formation and differentiation of red blood cells, reducing sensitivity to erythropoietin (EPO), and promoting IL-6 secretion by myeloma cells." (PMID 37250588, 2023). "Thus, it has a key role in systemic inflammation; TNF-alpha also has an essential role in anemia of chronic disease through stimulating ferritin synthesis, degradation and phagocytosis of red cells and direct inhibition of erythropoiesis (iron-restricted)." (PMID 35620179, 2022). "As one of the actions of TNF‐α is to suppress erythropoiesis, TNF‐α might have induced postoperative anaemia in our patient." (PMID 35846224, 2022). "TNF-α, IL-1, and endotoxin, which are substantially generated during inflammatory diseases, contribute to the development of anemia by reducing the lifespan of red blood cells (RBCs) and also by drastically decreasing plasma iron incorporation into freshly produced RBCs." (PMID 36106202, 2022). "In addition, previous research indicated that anti-TNF-α therapy can significantly induce the resolution of anemia and control disease activity." (PMID 35372478, 2022). "Numerous studies described the central role of TNF-α in the pathogenesis of anaemia." (PMID 36612220, 2022). "Given the haemolytic and bone marrow failure aspects of PNH, greater sensitivity to inflammatory cytokines such as TNF‐α may contribute to the development of postoperative anaemia." (PMID 35846224, 2022). "At this stage there is an increase in cytokines such as interleukin (IL)-6 and tumour necrosis factor (TNF)-alpha because of an increased acute phase and chronic inflammation, and additional problems emerge such as subfebrile fever, aches, fatigue, and chronic disease anemia." (PMID 35592192, 2022). "It is possible that the main contributors to anemia may be proinflammatory cytokines such as interleukin 6 (IL-6) and tumor necrosis factor α (TNF-α)." (PMID 34071554, 2021). "Aging is also associated with a chronic inflammatory phenotype that has been characterized by anemia, immunosenescense, and thrombocytosis, as well as overproduction of the inflammatory cytokines interleukin-1 (IL-1), tumor necrosis factorα (TNFα), and interleukin-6 (IL-6)." (PMID 34502021, 2021). "TNF-α contributes to anemia by inhibiting erythropoietin secretion and/or through direct toxicity on erythroid precursor cells, while interleukin-6 induces the production of hepcidin, which binds to ferroportin, thereby blocking the intestinal absorption of iron." (PMID 34071554, 2021).
anemia (continued). "Chronic inflammation has been shown to induce anemia, and we hypothesized the increase in TNFα, MCP-1, and IL-1α in the BM of Sost−/− mice would result in a decrease of mature erythrocytes (red blood cells, RBC)." (PMID 34502021, 2021). "Anaemia at presentation predicts poor response to anti-TNF therapy." (PMID 34083575, 2021). "For this reason, free TNF-α levels in cord blood should be examined in future studies to see whether they have a stronger relationship with fetal anemia than total TNF-α levels." (PMID 33995348, 2021). "Moreover, in an inflammatory cytokine-induced model of anemia in human hematopoietic stem/progenitor cells, it was found that TNFα-induction of anemia occurs via inhibition of autophagy in an mTOR-dependent manner." (PMID 32195258, 2020). "Since then, more studies have reported the relationship between TNF-α and anemia." (PMID 32667493, 2020). "Consistent with other's findings, the initial rise of IL6, followed by an increase of IL-12p70 and moderate changes in TNF-α and MCP-1 that are temporally associated with anemia, may play a role in its etiology." (PMID 33013831, 2020). "The increase of IL-12p70, TNF-α, and MCP-1 are temporally associated with anemia which might play a role in its etiology and inflammation." (PMID 33013831, 2020). "Based on these findings, banking P. falciparum-infected blood could exacerbate preexisting anaemia in blood recipients, through inhibition of erythropoietin activity by high TNF-α levels and low IL-10 levels." (PMID 33195706, 2020). "Overall, our results demonstrate that the TNFα/nSMase/ceramide pathway interferes with hematopoietic homeostasis providing new insights into hematopoietic cell fate determination as well as in inflammation-related anemia." (PMID 30546074, 2019). "While TNF-α is directly linked to the development of anemia in T. brucei infection, it appears not to be involved in T. congolense infection." (PMID 31824512, 2019). "However, during the final stage of infection, serum TNF-α reaches the same levels in both LT-α−/− and WT mice, concomitant with similar anemia levels in both mice groups." (PMID 29497418, 2018). "Likewise, COPD which is one of systematic inflammatory diseases is generally concomitant with the elevation of IL-1, IL-6 and TNF-a level in circulation inducing the development of anemia." (PMID 30139350, 2018). "A strong mediator of this programmed cell death and subsequent anemia is TNF." (PMID 30619242, 2018). "TNF-α could inhibit erythropoiesis through inducing dendritic cell proliferation, and the plasma TNF-α level might show a compensatory decrease in anemia rats." (PMID 29551975, 2018). "Senkyunolide I may interact with MAPK1, IL-1β, and TNF-α, which were also involved in anemia and vascular systems." (PMID 29551975, 2018). "Also, the severity of anemia has been suggested to be dependent on levels of TNF-α relative to anti-inflammatory cytokine IL-10." (PMID 29034874, 2017). "Multivariate analyses showed anaemia at delivery to be associated with a significantly higher TNF response to PHA (p = 0.01) at delivery, but no other associations were evident." (PMID 27653505, 2016). "Taken together, our studies demonstrate that decreased expression of DMT1 in intestinal mucosa leads to compromised absorption and transportation of iron and that blockade of TNF could rescue anemia and promote DMT1 expression in gut mucosa." (PMID 26572590, 2015). "In children with P. falciparum malaria, the by-product of hemoglobin digestion in infected red cells (hemozoin) is associated with the severity of anemia which is independent of circulating levels of the inflammatory cytokine tumor necrosis alpha (TNF-α)." (PMID 25781011, 2015). "In fact, the increased ratio of TNF over its soluble TNF-R2, not TNF levels per se, relates to the occurrence of infection-associated anemia." (PMID 26090446, 2015).
anemia (continued). "It was demonstrated that plasma mtDNA in MHD patients was positively associated with plasma TNF-α, and was associated with clinical events which have been proven participating in the inflammatory state in MHD patients, such as anemia, hypoproteinemia and hyperphosphatemia." (PMID 25485699, 2014). "Tumor necrosis factor alpha (TNF-α) is a major pro-inflammatory cytokine that functions as a mediator of acute inflammation, platelet activation and participation in the genesis of fever and anemia." (PMID 24632827, 2014). "The results of our study suggest that tocilizumab is superior to TNF-α inhibitors at improving the hematologic, iron-related and inflammatory parameters in RA patients and therefore should be particularly effective for patients with severe RA-anemia." (PMID 24286116, 2013). "Proinflammatory cytokines, particularly tumor necrosis factor α (TNF-α), interleukin 6 (IL-6) and IL-1 play important roles in the pathogenesis of RA and are thought to contribute to the development of RA-anemia by modulating iron metabolism and suppressing bone marrow erythropoiesis." (PMID 24286116, 2013). "Significant improvements in anemia and disease activity, and reductions in serum hepcidin-25 levels were observed within 2 weeks in both groups, and these effects were more pronounced in the tocilizumab group than in the TNF-α inhibitors group." (PMID 24286116, 2013). "The high TNF/IL-10 ratio observed in SMA suggests an imbalanced production of inflammatory cytokines that could contribute to anaemia." (PMID 22853732, 2012). "Ang-2 sensitization of endothelial cells to TNF may amplify secretion of endothelial cytokines, such as IL-6, that can promote anemia." (PMID 21364762, 2011). "Anemia of inflammation is characterized by decreased red blood cell production through a series of mechanisms, mediated in part by proinflammatory cytokines, particularly TNF-alpha and IL-6." (PMID 21738863, 2011). "Increased levels of proinflammatory cytokines like TNF-α are associated with maternal anemia in first time mothers but not in other women." (PMID 20098675, 2010). "On the other hand, the neighbouring TNF -308 A allele was associated with CM but not with severe malarial anaemia." (PMID 20846452, 2010). "Two studies were performed in Gambian children and results showed that the TNF -238 A allele was found to be associated with susceptibility to severe malarial anaemia but not to CM." (PMID 20846452, 2010). "In addition, recent data shows a correlation between elevated TNF-α, IL-6 and IL-8 levels and anemia in patients with chronic kidney disease." (PMID 20169072, 2010). "Thus, data related to TNFα-mediated inhibition of erythropoiesis show the indirect but also the direct involvement of this cytokine in anemia development." (PMID 20204172, 2009). "They showed that CLL-related anemia might result from the direct suppressive effect of TNFα on the erythroid development in early stages of erythropoiesis instead of an intrinsic defect of erythroid precursors to differentiate or to respond to Epo stimulation." (PMID 20204172, 2009). "Moreover, an increasing hemoglobin level has been observed in patients suffering from anemia of chronic disease after an anti-TNF treatment." (PMID 20204172, 2009). "This B-cell independent trypanosomiasis-induced anemia may be mediated by TNF, although the exact mode of action remains to be elucidated." (PMID 18688274, 2008). "TNF could have a crucial impact on anemia through its capacity to modulate the activation, growth and the phagocytic potential of macrophages involved in antibody independent erythrophagocytosis, a process which is dependent on IFNγ." (PMID 18688274, 2008). "Moreover, anemia can induce the release of inflammatory mediators, including TNF-α." (PMID 40177410, 2025). "Furthermore, it was found that cancer-related anemia may result from erythropoietin inhibition, facilitating the suppression of erythropoiesis by cytokines (IL-6, TNF-α)." (PMID 39372868, 2024).
anemia (continued). "Moreover, anemia can trigger the release of inflammatory factors like tumor necrosis factor-α." (PMID 38076531, 2023). "In severe P. falciparum malaria with corresponding high parasite density, a more intense pro-inflammatory environment with an elevation of cytokines including TNF-alpha, IL-1 and IL-6 may be created and this could contribute to the delayed erythrocytic response seen in P. falciparum induced anaemia." (PMID 36989322, 2023). "Moreover, anemia is more commonly seen in chronic inflammatory states that mediate increasing levels of plasma cytokines such as tumor necrosis factor, interleukin-1, and interferons, which may contribute to increased mortality." (PMID 35300753, 2022). "His disease course was refractory to azathioprine, anti-TNFα, and cyclosporin A. Two years and eight weeks after stopping azathioprine, but continuing infliximab therapy, he presented with fever, lymphadenopathies, splenomegaly, anemia, leucopenia, and ferritinemia (4361 μg/L)." (PMID 34768707, 2021). "While there is an inverse relationship between TNF-α and hemoglobin, this also adds consideration to the hypothesis that inflammation in H. pylori may cause the initial rise of TNF-α, which itself may potentially lead to anemia." (PMID 34307412, 2021). "Moreover, TNF α decreases iron incorporation into erythrocytes, thus leading to anemia." (PMID 34684083, 2021). "However, in many patients enhanced formation of pro-inflammatory cytokines including interleukin 1 (IL-1), tumor necrosis factor alpha (TNF-α) or interferon gamma (IFN-γ) leads to the development of functional iron deficiency (ID) and anemia of chronic disease (ACD)." (PMID 34458328, 2021). "As TNFα inhibits erythropoiesis, elevated TNFα may contribute to anemia in HIV." (PMID 34067023, 2021). "Subsequently, chronic inflammation can lead to anemia through several pathways, e.g., induction of the master regulator of iron homeostasis hepcidin by Interleukin-6 or the inhibition of erythropoietin formation in the kidney mediated by Interleukin-1 and TNF-alpha." (PMID 32903529, 2020). "Thus, HIV, its virulent proteins, TB, heroin, cocaine and proinflammatory cytokines including IL-1, IL-6, TNF-α altogether could be responsible for anemia severity among HIV+ TB+ ISUs." (PMID 33911826, 2020). "In normal pregnancy Th1 cytokine responses are generally suppressed, but PM can result in placental elevation of tumor necrosis factor α (TNF-α), which is associated with both anemia and LBW, while increased interferon γ (IFN-γ) levels could mediate either protective or pathogenic effects." (PMID 32726331, 2020). "Some inflammatory cytokines, such as tumor necrosis alpha (TNF-α) and interleukin (IL-6), were reported to inhibit the maturation of erythrocytes through suppression of hematopoietic system in the marrow, resulting in anemia after hematopoietic stem cell transplantation." (PMID 33537231, 2020). "Altogether, these findings corroborate the hypothesis that the anemia observed in mice infected with T. cruzi SC2005 is caused by an impairment in bone marrow function, induced by TNF-α and IFN-γ, which lead to occurrence of extramedullary hematopoiesis in mice livers as a compensatory mechanism." (PMID 33329529, 2020). "In cancer, several cytokines namely tumor necrosis factor -α (TNF-α), transforming growth factor -β (TGF-β), interleukin-1 (IL-1), IL-6 and interferon-γ interfere normal erythrocyte production by modulating iron metabolism and blunting erythropoietin effect thereby causing anemia." (PMID 31387568, 2019). "Therefore, our data suggest that TNF-α stimulates the expression of hepcidin in IBD patients, resulting in aggravated anemia and that blockage of TNF-α or the caspase-3/8 and NF-κB pathways could downregulate hepcidin expression." (PMID 31814801, 2019). "Interestingly, the application of anti-TNF-α mAb could effectively suppress hepcidin expression in active CD patients and significantly improve the status of anemia." (PMID 31814801, 2019).
anemia (continued). "Inflammatory cytokines such as interferon-γ, tumor necrosis factor-α, interleukin-1, and interleukin-10 might compromise iron metabolism, impair erythroid progenitor cell proliferation, and blunt erythropoietin response to anemia." (PMID 29237417, 2017). "Multiple factors including psychological factors are involved in dialysis-related fatigue, such as anemia, hemodynamic instability, presence of cardio- and cerebrovascular diseases, nutritional status, and inflammatory conditions accompanying increased levels of hsCRP and IL-6, and TNF-α." (PMID 28902900, 2017). "Additionally, it is also supposed that TNF could induce the anemia in IBD patients by blocking the DMT1 expression." (PMID 26572590, 2015). "Thus, the relatively low serum hepcidin-25 levels in patients with RA-anemia may partially be due to a balance between opposing effects of hepcidin-regulating cytokines such as IL-6 and TNF-α." (PMID 24286116, 2013). "We hypothesized that in H. pylori infected children without the known common causes of ID, increased gastric concentrations of IL-1β and/or TNF-α could be predictors for low blood concentrations of ferritin and haemoglobin, markers of early depletion of iron stores and anaemia, respectively." (PMID 23451225, 2013). "In fact, TNF-α may also play an important role in RA-anemia via hepcidin-independent pathways." (PMID 24286116, 2013). "In particular the production of endogenous pyrogens such as TNF, IL-1β and IL-6 following IFN-γ stimulation of monocytes/macrophages may be responsible for fever induction and sustained IL-1β production may be associated with anaemia." (PMID 23046548, 2012). "Moreover, anemia in children with solid tumours was related to IFNγ and TNFα." (PMID 20204172, 2009). "Studies have shown that the likelihood of anemia occurrence is lower in patients receiving TNF-α treatment, possibly due to TNF-α’s role in alleviating inflammation." (PMID 39908327, 2025). "Therefore, TNF-α treatment may be considered as a priority for AS with concurrent anemia to control inflammation, reduce disease activity, and subsequently lower the incidence of anemia." (PMID 39908327, 2025). "Inflammatory cytokines, especially TNF-α and IL-6, further exacerbate CKD progression and disrupt iron homeostasis, thereby influencing anemia severity." (PMID 38612557, 2024). "Comparisons of patients with mild TB and mod-sev disease or anemia, demonstrated that Th1 (IL-2, IFN-γ, and TNF-α) as well as Th2 (IL-4, IL-13, and IL-10) and Th17 responses were higher in mild TB disease." (PMID 38162636, 2023). "Hence, the proposed mechanism suggests that iron deficiency anemia might indirectly regulate LRG1 expression, possibly by upregulating HIF-1α expression, which regulates direct targets of LRG1 promoter including IL-6 and TNFα." (PMID 37513518, 2023). "Considering anemia, the group of SLE-a patients showed a strong correlation of RDW with serum IL-6 (r = 0.894, p < 0.001) in addition to PLR with TNF (r = 0.743, p < 0.025) and an inverse correlation with C3 complement (r = 0.538, p < 0.05)." (PMID 35620179, 2022). "Cytokines and inflammatory markers including TNF-α, IFN-Υ, hepcidin, and ILs contribute to the development of anemia in patients with chronic diseases." (PMID 36106202, 2022). "These molecules contribute to infection-induced anemia, as Gal-3 induce erythrophagocytosis, while MIF promotes the production of pro-inflammatory cytokines, including TNF." (PMID 36420267, 2022). "Recent studies have shown that TNF-α can upregulate PU.1 and GATA2 in HSPCs to inhibit erythroid differentiation and lead to anemia." (PMID 36567722, 2022). "We show that animals with active L. infantum infection had anemia, leukocytosis with neutrophilia and an increase in the gene expression levels of IFN-γ and TNF in the bone marrow." (PMID 34442696, 2021).